GABARAPL1 (GABA type A receptor associated protein like 1)
Diseases named in the same sentence as GABARAPL1 in open-access papers (continued):
Sharing a sentence is not in itself a finding about the gene and the disease.
tumor (46 papers, 2010 to 2025). "We observed that targeting GABARAPL1 after irradiation significantly reduced regrowth of the tumours which was again associated with reduced vessel density." (PMID 34859607, 2021). "GABARAPL1 deficiency resulted in delayed tumour growth and was associated with reduced vessel density (31% difference, p = 0.005, as assessed by 9F1 immunohistochemistry." (PMID 34859607, 2021). "The GABA type a receptor associated protein like 1 (GABARAPL1) is known to function as a tumor suppressor in BC by maintaining normal cellular metabolism." (PMID 29719590, 2018). "The finding that the expression of Akt and GABARAPL1 is inversely associated in CaP tumor tissues suggests that the inactivation of GABARAPL1 by Akt, most likely through FOXOs, is involved in CaP progression." (PMID 27966458, 2017). "Among the CaP tumor tissues, a progressive loss of GABARAPL1 was found with increased Gleason scores." (PMID 27966458, 2017). "RNAPolII association at the promoters of MAFbx/Atrogin1, MuRF1, and GABARAPL1 increased in muscles from (−)-JQ1-treated C26-tumor-bearing mice when compared to control muscles, in agreement with the enhanced RNA transcript levels." (PMID 29167426, 2017). "Some evidence suggests that GABARAPL1 expression is lower in HCC tissues than in adjacent non-tumor tissues and that there is an association between low GABARAPL1 expression and poor prognosis in HCC patients." (PMID 26561802, 2015). "GabarapL1 has also been implicated in autophagosome fusion with lysosome, and these functions are supposed to contribute to the degradation of oncogenic proteins and exert tumour-suppressive functions." (PMID 36901549, 2023). "Importantly, the delayed tumour growth was partially rescued if the same animal was implanted with a control tumour as well as a GABARAPL1 deficient tumour." (PMID 34859607, 2021). "Again, GABARAPL1 deficiency results in delayed tumour growth compared to control tumours." (PMID 34859607, 2021). "Extrapolated to cancer patients this could mean that GABARAPL1 blocking antibodies could inhibit angiogenesis or neovascularisation and thereby inhibit tumour growth and increase susceptibility to therapeutic interventions." (PMID 34859607, 2021). "In addition, the reduced vessel density and increased tumour necrosis of GABARAPL1‐deficient tumours was also resolved." (PMID 34859607, 2021). "Interestingly, morphology assessment using H&E staining indicated that GABARAPL1 deficient tumours displayed increased tumour necrosis." (PMID 34859607, 2021). "Interestingly, the G116A mutation inhibited GABARAPL1 tumor suppressive function on several phenotypes apart from migration in MCF7 cells in vitro." (PMID 28915569, 2017). "As GABARAPL1 overexpression was associated with a decreased cancer cell growth rate, it can be expected that its expression might also be altered in tumour tissues." (PMID 20197771, 2010). "Finally, the effects of GABARAPL1 deficiency on tumour growth and TME might be caused by cell intrinsic changes, rather than by EVs." (PMID 34859607, 2021). "GABARAPL1 participates in various mechanisms such as autophagy, cell death, cell proliferation and tumor progression by mediating the transport of proteins or vesicles." (PMID 41040512, 2025). "The expression of GABARAPL1 is upregulated in response to tumour‐induced hypoxia, thereby enhancing the secretion of exosomes and growth factors, consequently facilitating tumour angiogenesis." (PMID 40095893, 2025). "At the endpoint, the levels of GABARAPL1 in the tumor tissues from mice were confirmed by western blot, which confirmed overexpression of GABARAPL1 in mouse tumor tissues." (PMID 38234672, 2024). "The heatmap ofclinical-pathological correlations demonstrated a significantcorrelation between high and low expression of GABARAPL1 and patient age and tumor growth in UM." (PMID 39308299, 2024). "Correspondingly, GABARAPL1 has been reported to promote tumor growth by increasing FL-AR/AR-V transcription activity." (PMID 36937439, 2023).
tumor (continued). "Of the 21 MRGs, ATG9A, PGAM5, SQSTM1, and GABARAPL1 were differentially expressed at the transcriptomic level between tumor and normal tissues." (PMID 36292980, 2022). "Among these four genes, GABARAPL1 was downregulated in HCC tumor‐repopulating cells (TRC; a type of CSLC)." (PMID 36062307, 2022). "For this, we allowed xenografts to reach a volume of 150 mm3, irradiated the tumours with a single, tumour specific dose of 10 Gy followed by GABARAPL1 knockdown through doxycycline administration." (PMID 34859607, 2021). "To confirm the reliability of the identified gene signature, we examined the ULK2 and GABARAPL1 expression levels by qRT-PCR, WB, and IHC using 8 pairs of OC tumor tissues and paracancerous tissues." (PMID 34041016, 2021). "In conclusion, we show for the first time that GABARAPL1 is important for tumour development, through secretion of a specific subset of pro‐angiogenic EVs, marked by GABARAPL1 expression." (PMID 34859607, 2021). "Next, we questioned if GABARAPL1 targeting would yield beneficial effects in a more clinically relevant situation (e.g., targeting an existing tumour)." (PMID 34859607, 2021). "Autophagy activation observed previously in tumor-bearing mice was recapitulated in cancer patients including increase of LC3b and Gabarapl1 as well as active ULK-1, which were accompanied by reduced p62 as expected." (PMID 34950660, 2021). "Tumour xenografts of doxycycline inducible GABARAPL1 knockdown cells display impaired vascularisation that results in decreased tumour growth, elevated tumour necrosis and increased therapy efficacy." (PMID 34859607, 2021). "In this study we describe that GABARAPL1 is required for the secretion of EVs and growth factors during hypoxia and thereby contributes to tumour growth in various tumour cell types." (PMID 34859607, 2021). "The doxycycline inducible promoter allows establishment of tumours with intact GABARAPL1 expression, which can be transiently blocked by addition of doxycycline to the drinking water." (PMID 34859607, 2021). "We observed that GABARAPL1 knockdown reduced tumour growth as illustrated by an increase in tumour doubling times from 11 to 15 days (36%)." (PMID 34859607, 2021). "The results showed that the ULK2 and GABARAPL1 mRNA in the tumor tissues were significantly downregulated compared with those in the paracancerous tissues (p<0.05)." (PMID 34041016, 2021). "This was supported by our observation in vivo that inhibition of GABARAPL1 following irradiation contributed to delayed tumour regrowth." (PMID 34859607, 2021). "In conclusion, we show a unique role for GABARAPL1 in tumour progression through secretion of EVs by hypoxic cells." (PMID 34859607, 2021). "Overexpression of GABARAPL1 led to a decrease in tumor size confirming previous results obtained in nude mice." (PMID 28915569, 2017). "In order to characterize the effect of GABARAPL1 conjugation to autophagosomes on cancer progression in vivo, we studied tumor growth following injection of GABARAPL1 and GABARAPL1 G116A-overexpressing cells into Rag γ/c mice." (PMID 28915569, 2017). "GABARAPL1 plays important roles in protein interaction and transportation, as well as autophagy, cell proliferation and tumor progression." (PMID 27966458, 2017). "All these results indicated that GABARAPL1 acted as a tumor promoter in TNBC and it had a tremendous potential as a therapeutic target against TNBC." (PMID 29088804, 2017). "In order to confirm the overexpression of GABARAPL1 and GABARAPL1 G116A in the respective tumor, we next wanted to analyze levels of these proteins in tumors by IHC." (PMID 28915569, 2017). "In contrast, very low GABARAPL1 staining was observed in CaP tumor tissues compared to high expression in adjacent non-tumor tissues." (PMID 27966458, 2017). "The relative GABARAPL1 expression histo-scores in tumor tissues and adjacent non-tumor tissues were calculated by the multiplication of the intensity and area of the IHC staining." (PMID 27966458, 2017).
tumor (continued). "Overall, GABARAPL1 mRNA expression levels in CaP tumor tissues were significantly lower than those in the benign prostate tissues (P < 0.001)." (PMID 27966458, 2017). "On the other hand, the ectopic over-expression of GABARAPL1 inhibits cancer cell proliferation and tumor growth in mice." (PMID 27098372, 2016). "An inverse correlation (r = −0.57) was also observed between GABARAPL1 mRNA and tumor stage while a very poor correlation was determined between GABARAP or GABARAPL2 expression levels and the tumor grade (respectively r = −0.3 and r = −0.1)." (PMID 26474850, 2015). "The transcript levels of LC3, ATG12, and Gabarapl1 genes involved in autophagic vacuole formation, increased 3.04-fold, 2.685-fold, and 1.820-fold in tumor tissues, respectively." (PMID 24527027, 2014). "Gabarapl1 mRNA levels were found to be significantly lower in tumours presenting a high histological grade, with a lymph node-positive (pN+) and oestrogen and/or progesterone receptor-negative status." (PMID 20197771, 2010). "Interestingly, research has indicated that hypoxia induces GABARAPL1 expression, which promotes the secretion of exosomes and growth factors, ultimately facilitating tumor angiogenesis and tumor growth." (PMID 40951345, 2025). "However, in OC, higher GABARAPL1 expression correlates with poorer patient outcomes, suggesting a complex and context-dependent role in tumor progression." (PMID 40539060, 2025). "Additionally, GABARAPL1 plays multifunctional roles in phagocytosis, cell motility, intracellular transport, and oncogenic/tumor-suppressive regulation." (PMID 40951345, 2025). "By degrading unnecessary protein aggregates and organelles, GABARAPL1 may play a protective role against tumor progression." (PMID 41040512, 2025). "Interestingly, the levels of ATG4B, LC3II/LC3I, and SQSTM1/P62 were all up-regulated in mouse tumor tissues that overexpressed GABARAPL1, suggesting an up-regulation of autophagy in the tumor." (PMID 38234672, 2024). "The overexpression of GABARAPL1 speeded up tumor growth in nude mice." (PMID 38234672, 2024). "This suggests that GABARAPL1 possibly exerts an anti-tumor effect in NPC via HIF-2α." (PMID 38234672, 2024). "Moreover,GABARAPL1 can modulate epithelial-mesenchymaltransition in tumor cells by regulating autophagy." (PMID 39308299, 2024). "Furthermore, we show that tumour growth and regrowth after irradiation is delayed after silencing GABARAPL1 in tumour xenografts, as a result of reduced vascularisation and enhanced tumour necrosis." (PMID 34859607, 2021). "Since we found that hypoxic cell‐derived GABARAPL1+ EVs contribute to tumour growth and GABARAPL1 is present on the outer membrane of secreted EVs, GABARAPL1 might also be a new therapeutic target." (PMID 34859607, 2021). "Previous results have shown that GABARAPL-1 knockdown leads to decreased autophagy flux and lysosome number as well as increased cell growth, while GABARAPL-1 overexpression inhibits cancer cell proliferation and tumor formation in nude mice via Wnt/β-catenin pathway." (PMID 35201430, 2021). "Whether GABA drives downstream signaling like GABARAPL1 in cancer cells needs to be examined, but if so, it may affect tumor promotion such as NMDAR signaling." (PMID 34445736, 2021). "Surprisingly, in contrast to HT29 xenografts, GABARAPL1 deficient U87 tumours did not grow slower compared to control tumours, despite a reduced vessel density." (PMID 34859607, 2021). "Although in vitro experiments suggest that the observed effects on tumour development are GABARAPL1+ EV related, it is challenging to discriminate if the observed effects in tumour growth in vivo are solely due to GABARAPL1+ EV or also caused by cell intrinsic changes." (PMID 34859607, 2021). "Apart from its function in autophagy, GABARAPL1 plays a potential role during tumor progression." (PMID 32801338, 2020). "An inverse relationship was also observed between GABARAPL1 mRNA and tumor stage." (PMID 33194339, 2020).
tumor (continued). "Given the function of GABARAPL1 in autophagy and cancer, the purpose of our study was to: i) study the role of GABARAPL1 during early and late stages of autophagy and, ii) determine the involvement of GABARAPL1 conjugation to autophagosomes in its tumor suppressive function." (PMID 28915569, 2017). "It has also been shown that GABARAPL1 overexpression inhibits tumor growth in vivo and mediate the degradation of DVL2 (Dishevelled 2) through selective autophagy leading to the inhibition of the Wnt pathway whose deregulation has been described to be involved in various diseases such as cancer." (PMID 28915569, 2017). "Overexpression of GABARAPL1 G116A also led to a significant decrease in tumor growth." (PMID 28915569, 2017). "To investigate whether the expression of Akt and GABARAPL1 is correlated in clinical samples, we assessed their expression in ten pairs of primary CaP tumor tissues and matched adjacent non-tumor tissues by immunohistochemistry staining." (PMID 27966458, 2017). "GABARAPL1 and GABARAPL1 G116A could present a tumor suppressor role through the inhibition of MTOR which has been previously shown to be involved in cell proliferation and tumor progression." (PMID 28915569, 2017). "Our findings demonstrate that GABARAPL1 acts as a tumor promoter in TNBC partly through MTDH." (PMID 29088804, 2017). "We then studied the effect of GABARAPL1 on tumor metastasis in vivo." (PMID 29088804, 2017). "Furthermore, the role of GABARAPL1 was assessed in vivo using a nude mouse xenograft tumor model." (PMID 38234672, 2024). "Importantly, overexpression of GABARAPL1 slowed tumor growth." (PMID 38234672, 2024). "Moreover, autophagy and autophagy proteins such as p62, GABARAP or GABARAPL1 are conserved, suggesting that our study could be transposed to human vaccinations when tumor-derived antigens are used." (PMID 36139357, 2022). "However, it is unclear how GABARAPL-1 regulates both autophagy and tumor growth." (PMID 35201430, 2021). "However, we are aware that further studies are required to determine whether the modulation of the NMD pathway during the EMT could contribute to the induction of selective autophagy mediated by GABARAPL1 and its consequences on tumor progression." (PMID 34680418, 2021). "Indeed, we found that the decreased growth of GABARAPL1 knockdown tumours could be rescued partially by circulating factors secreted by control tumours in a GABARAPL1 dependent manner." (PMID 34859607, 2021). "Interestingly, we noted that GABARAPL1 expression levels seemed to be inversely correlated with tumor growth, but we cannot exclude that there are other intrinsic differences which may influence tumor growth unrelated to GABARAPL1 expression." (PMID 28915569, 2017). "Compared to normal samples, the expression of all genes, except for GABARAPL1, was significantly higher in OSCC tumor tissues." (PMID 40951345, 2025). "When GABARAPL1 was overexpressed, the autophagosome formation indicator LC3 was induced, HIF-2α was decreased, NPC cell apoptosis was enhanced, and tumor cell growth was inhibited in the cultured NPC cells and the mouse xenograft model." (PMID 38234672, 2024). "Overexpression of GABARAPL1 led to increased apoptosis in NPC cells and slowed tumor growth in nude mice." (PMID 38234672, 2024). "Conversely, a pervasive decrement was witnessed in the expression of GABARAPL1, MAP1LC3C, VTN, and IL6 in nearly all tumor specimens relative to their paired normal tissue counterparts." (PMID 38460947, 2024). "Further investigations are needed to demonstrate the antitumor effect of tumor-antigens fused with GABARAP and GABARAPL1." (PMID 36139357, 2022). "In this work, we investigated the potential role of GABARAP and GABARAPL1, two members of the autophagic ATG8 family proteins, as surrogate tumor antigen delivery vectors to prime antitumor T cells." (PMID 36139357, 2022).
tumor (continued). "We therefore investigated FoxO3 recruitment to MAFbx/Atrogin1, MuRF1, and GABARAPL1 promoters in skeletal muscles from control and (−)-JQ1 and (+)-JQ1-treated C26-tumor-bearing mice by ChIP qPCR." (PMID 29167426, 2017). "Autophagy undergoes both short- and long-term activation during cachexia; accordingly autophagy-related transcripts Bnip3, LC3b, GABARAPL1, Atg7, and CathepsinL were considerably increased in vehicle and (−)-JQ1-treated C26-tumor-bearing mice." (PMID 29167426, 2017). "In order to conclude about the effect of GABARAPL1 and GABARAPL1 G116A in cancer, we studied in vivo the tumor growth after injection of MCF-7 C, GABARAPL1 or GABARAPL1 G116A cells into Rag γ/c mice." (PMID 28915569, 2017). "For example, we and others have demonstrated that GABARAPL1 is involved in anterograde trafficking of several receptors, including EGFR, which might influence tumour cell proliferation." (PMID 34859607, 2021). "We show that the G116A mutation impaired GABARAPL1 function in autophagosome/lysosome fusion and inhibited lysosome activity but did not alter MTOR and ULK1 activities or tumor growth in vivo." (PMID 28915569, 2017). "Some publications have suggested that GABARAPL1 and GABARAP might also be involved in tumour development." (PMID 20197771, 2010). "Overexpression of GABARAPL1 G116A also led to a decrease in tumor growth suggesting that GABARAPL1 conjugation to autophagosomes could not be necessary for its tumor suppressive function in vitro as well as in vivo." (PMID 28915569, 2017). "But, we cannot exclude that GABARAPL1 might present a tumor suppressor role through functions independent of its role in autophagy." (PMID 28915569, 2017). "Thus, inhibition of GABARAPL1 could potentially alter tumour growth by affecting intrinsic factors, for example, downstream signalling of EGFR, leading to decreased cell proliferation, resulting in decreased tumour growth." (PMID 34859607, 2021). "In the HPA database, NRAS, STEAP3, and ALOX5 proteins are significantly expressed in tumor tissues, but the difference in the expression of ZFP36 and GABARAPL1 proteins is not obvious." (PMID 34868262, 2021). "Moreover, given that GABARAPL1 G116A, which predominately cannot conjugate to autophagosomes and interacts less with SQSTM1, still presented a tumor suppressor role, we might think that GABARAPL1 function in selective autophagy is not essential for its tumor suppressive function." (PMID 28915569, 2017).